RSPO3 (R-spondin 3)
Diseases named in the same sentence as RSPO3 in open-access papers (continued):
Sharing a sentence is not in itself a finding about the gene and the disease.
tumor (continued). "This revealed that RSPO3‐driven tumors are distinct, as the poorly differentiated tumor morphology and metastatic potential were observed in RSPO3‐driven tumorigenesis exclusively, further substantiated by differentiating gene expression profiles." (PMID 36106661, 2022). "Other low frequency actionable fusions namely, AGK-BRAF, FIP1L1-PDGFRA, FNDC3B-PIK3CA, RET-NCOA4, SND1-BRAF, TMEM178B-MET, TMEM178B-BRAF, KANK1-NTRK3, EIF3E-RSPO2 and PTPRK -RSPO3 have been previously reported as rare fusions in tumours of other type." (PMID 35984852, 2022). "Inhibition of RSPO3 with function-blocking antibodies in PTPRK-RSPO3-fusion tumor xenografts inhibited growth and promoted epithelial differentiation." (PMID 35358569, 2022). "A previous report identified a PTPRK-RSPO3 fusion gene in CRC and demonstrated that targeting RSPO3 in PTPRK-RSPO3 fusion-positive human tumor xenografts inhibited tumor growth and promoted differentiation." (PMID 35751785, 2022). "A total 379 tumor solid samples, and of the 372 samples, excluding the 7 fusion-positive samples, 186 samples expressing less than 50% RSPO3 mRNA expression were selected as control." (PMID 36129915, 2022). "Encouragingly, antibody-mediated blockade of RSPO3 inhibited the growth of PTPRK-RSPO3-fusion-positive human tumour xenografts, compromising the expression of stemness genes (e.g., LGR5, ASCL2, LRIG1, TERT) and promoting differentiation." (PMID 33673710, 2021). "The polyps of the Ptprk-Rspo3 in vivo model were widespread in the small intestine and harbored at least one copy of the inversion in most of the tumor cells, suggesting a cell-intrinsic advantage of carrying the fusion." (PMID 34585724, 2021). "Inversely, targeted anti-RSPO3 treatment in a PTPRK-RSPO3 xenograft CRC model was shown to induce tumor differentiation whilst reducing growth, stem cell marker expression and canonical Wnt pathway activity." (PMID 34663878, 2021). "The RSPO-fusion tumours exhibited a tissue compartmental shift in expression with epithelial localisation of transcripts, whereas RSPO-high tumours exhibited marked upregulation of RSPO3 expression from the desmoplastic stroma." (PMID 31563876, 2020). "For example, treatment with anti-RSPO3 antibody has been shown to result in inhibition of xenograft tumor growth with tumor regression in some cases." (PMID 33202731, 2020). "Tumours with outlier RSPO3 expression were profiled using both targeted RSPO3 RNA sequencing to identify fusion genes and ISH to visualise the origin of the RSPO3 signal in these samples." (PMID 31563876, 2020). "We and others have reported that RSPO3 is highly expressed in certain human tumors, and RSPO3 antagonism inhibits tumor growth in animal models." (PMID 32160239, 2020). "We identified six tumours with outlier RSPO3 expression, four of which had detectable RSPO3 fusions." (PMID 31563876, 2020). "Given the literature on RSPO3 as a Wnt agonist, it is possible that the increased invasiveness we observe in RSPO3-silenced tumours is due to decreased signaling through one of the Wnt pathways." (PMID 30987640, 2019). "Taken together, these studies suggest a potentially tumour-promoting role for RSPO3 in a tissue-specific fashion." (PMID 30987640, 2019). "Upon treatment of these tumours with anti-RSPO3 antibody using patient-derived xenograft models, expression of LGR5 and ASCL2 were highly downregulated, whereas MYC, AXIN2 and CCND1 (cyclin D1) did not rank among the top 100 downregulated genes." (PMID 30792270, 2019). "According to these findings, it was suggested that a stem cell compartment drives PTPRK-RSPO3-positive tumor cell growth and targets RSPO3, inhibiting this tumor stem cell compartment." (PMID 29652830, 2018). "Combining anti-Rspo3 with paclitaxel resulted in an enlarged cellular morphology that closely resembles that of endoreduplication and mitotic catastrophe, while reducing tumor cell density." (PMID 29127379, 2017).
tumor (continued). "In CRC PDX models, the expression of murine Rspo3 in stromal cells of the tumor microenvironment was detectable by qPCR." (PMID 29127379, 2017). "Most importantly, both Rspo2 and Rspo3 fusions represent druggable cancer drivers, as the tumours are sensitive to Wnt-targeted therapy with a meaningful therapeutic window." (PMID 28695896, 2017). "Our study shows that indeed, endogenous RSPO2 and RSPO3 rearrangements can initiate tumour growth in the intestine, but that they drive disease on a molecularly distinct course compared to Apc mutations." (PMID 28695896, 2017). "Here, we demonstrate that the overall cancer stem cell population was dramatically reduced in tumor cells previously treated with anti-Rspo3 plus nab-paclitaxel." (PMID 29127379, 2017). "Here we demonstrate that Rspo3 derived from the tumor microenvironment can be inhibited to induce a profound anti-tumor response." (PMID 29127379, 2017). "This suggests that the promotion of differentiated, chemo-sensitive tumor cells is a gradual process that requires successive exposure to the combination of anti-Rspo3 with paclitaxel." (PMID 29127379, 2017). "The VACO6 xenograft model demonstrates tumor growth inhibition when exposed to anti-RSPO3 alone or in combination with the topoisomerase inhibitor irinotecan or alternatively in combination with nab-paclitaxel." (PMID 29127379, 2017). "Altogether, our study provides direct evidence that endogenous Rspo2 and Rspo3 chromosome rearrangements can initiate and maintain tumour development, and indicate a viable therapeutic window for LGK974 treatment of RSPO-fusion cancers." (PMID 28695896, 2017). "In tumor cells Foxp3 low expression would explain high transcriptional activity of Runx1 on Rspo3 promoter." (PMID 26735887, 2016). "Genes with Lasso regression coefficients |β| > 10 include LETMD1, a known oncogene, the known tumor suppressor CDKN1B, as well as several other genes whose variants have been linked with other cancers, such as RSPO3." (PMID 27124395, 2016). "Since R-spondin sensitizes cells to Wnt ligands through inhibiting ZNRF3/RNF43, tumor cells harboring RSPO2/RSPO3 translocations should be sensitive to either direction inhibition of RSPO2/RSPO3 or inhibition of Wnt ligand secretion by porcupine inhibitors." (PMID 27338477, 2016). "To address the question of how this oncogene expression is differentially regulated in normal and tumor mammary epithelial cells, we analyze the promoter region of RSPO3." (PMID 26735887, 2016). "To evaluate if the observed DNA/Runx1 interaction is biologically relevant for Rspo3 expression, we altered Runx1 expression levels in tumor and normal cell lines and evaluated Rspo3 expression and cell behaviour changes." (PMID 26735887, 2016). "In addition, RSPO3 suppression inhibits MKN45 tumor peritoneal seeding and ascites in vivo, which accompanied by improving the animal health, behavior and weight of mice." (PMID 38581123, 2024). "Our group showed that RUNX1 regulates R-Spondin 3 (RSPO3), promoting tumor growth and motility." (PMID 36766786, 2023). "In contrast, tumors targeting RSPO3 demethylated QBC939 had a lower degree of tumor infiltration." (PMID 37932819, 2023). "Thus, RSPO3 co‐expression with WNT1 affects tumor morphology, and accordingly, distant lung metastases were found in three of nine RSPO3/WNT1 mice." (PMID 36106661, 2022). "Interestingly, combining an anti-RSPO3 antibody (OMP-131R10) with paclitaxel also reduced tumor growth and nuclear β-catenin expression in 8 APC mutant CRC PDX models when compared to monotherapy." (PMID 35204808, 2022). "In this report, we provide evidence supporting a tumor-suppressive role for RSPO3." (PMID 30987640, 2019). "In this system, they reported a moderate upregulation of classic Wnt pathway targets, such as Lgr5 and Axin2 in the intestine, spheroid changes in organoids, and a tumour response driven predominantly by paracrine Rspo3 signals from a minor sub-population of cells." (PMID 28695896, 2017).
tumor (continued). "Our data indicates that reduced Runx1 transcriptional activity downregulates Rspo3 oncogene expression, upregulates GJA1 tumor suppressor gene expression, significantly delays tumor cell migration and wanes cell number, in a susceptible manner to Foxp3's stalling activity." (PMID 26735887, 2016). "Moreover, heterogeneity and tumour‐stroma crosstalk, particularly the interaction of CAFs with tumour cells via GDF15/RSPO3, which fosters an immunosuppressive microenvironment around tumour cells, require further confirmation through additional functional experiments." (PMID 40292733, 2025). "In addition, RSPO3 suppression inhibits MKN45 tumor peritoneal seeding and ascites in vivo." (PMID 38581123, 2024). "In addition, RSPO3 suppression inhibited MKN45 tumor peritoneal seeding in vivo." (PMID 38581123, 2024). "However, several studies have indicated that RSPO3 functions as a tumor progression suppressor." (PMID 37932819, 2023). "The expression of RSPO3, ALPP, VEGFC, ANXA8, HES2, GLP2R, and KRT14 in normal tissues was significantly higher than that in tumor tissues." (PMID 38240936, 2024). "One cell line (KPNSI9S) has a high expression of RSPO3 while six cell lines express RSPO4 at moderate levels, suggesting that they were expressed in tumor cells in the primary tumors." (PMID 39065640, 2024). "Therefore, whether RSPO3 inhibition would inhibit GC tumor peritoneal seeding in vivo was explored." (PMID 38581123, 2024). "This means that human CRC is a sensitive tumor for WNT-targeted treatment, suggesting that RSPO3 fusion gene can be an effective therapeutic target." (PMID 36129915, 2022). "Reduced tumor growth and increased cancer cell differentiation were observed in SNU-1411 (RSPO3-fusion), AsPC1 and HPAF-II (both RNF43-mutant) xenograft models, with a therapeutic window versus Wnt homeostatic functions." (PMID 36922934, 2022). "Classic examples of this phenomenon are nucleophosmin 1 (NPM1) and PTPRK, putative tumor suppressor genes that are recurrently fused to ALK1 and RSPO3, respectively." (PMID 34585724, 2021). "Among the R-spondin genes, RSPO2 expression is clearly correlated with TCF7L1, but only in normal tissue, while RSPO3 expression is less strongly correlated with TCF7L1, both in normal and tumor tissue." (PMID 32403323, 2020). "In these gene fusions, the signal sequence of PTPRK is fused to RSPO3, reducing PTPRK and leading to elevated RSPO3 protein levels, which in transgenic mouse models are sufficient to drive tumor initiation." (PMID 31934854, 2020). "WNT pathway blockade with porcupine inhibitors is effective in RSPO3-rearranged CRC preclinical models and clinical trials in patients with RSPO2/3-fusion-positive tumours of any histological origin are ongoing (NCT01351103)." (PMID 31097696, 2019). "When these RSPO3–PTPRK fusions were targeted using antibodies generated against RSPO3 in xenografts, tumour growth was inhibited." (PMID 30987640, 2019). "In fact, targeting RSPO3 in PTPRK-RSPO3-fusion positive tumor xenografts inhibits tumor growth and promotes tumor cell differentiation." (PMID 29652830, 2018). "Runx1 is able to promote RSPO3 gene expression and inhibit GJA1 gene expression on tumor epithelial cells, depending on Foxp3 availability." (PMID 26735887, 2016). "In contrast, RSPO3 derived from myCAFs can up-regulate EGR1 expression in tumor cells, promoting the conversion of gastric cancer cells into the MP7 state and thereby enhancing the tumor’s invasiveness and drug resistance." (PMID 41583453, 2025). "Interestingly, several oncogenic proteins were elevated in plasma, such as SCRN1 and RSPO3, whereas previous studies determine their overexpression in CRC tumor tissue." (PMID 37228491, 2023). "Consistent with this idea, we find that the expression levels of ETV4, ERG, PIK3CA, and RSPO3 were elevated ~ 80–800-, ~ 25-, ~ 8-, and ~ 10–30-fold compared to the fusion-negative group of the same tumor type, respectively." (PMID 32631391, 2020).
tumor (continued). "We show that both Rspo2 and Rspo3 fusion events are sufficient to initiate hyperplasia and tumour development in vivo, without additional cooperating genetic events." (PMID 28695896, 2017). "According to GO analysis, the RSPO3+ TC has potential for cell migration, the fibroblast-like TC remodels the ECM, which can aid cell migration, and the proliferating, S-phase, and proliferating myoblast-like TCs contribute to tumor growth through cell proliferation." (PMID 41373578, 2025). "Importantly, we found novel protein changes including high levels of oncogenic proteins such as R-Spondin 3 (RSPO3) and secernin 1 (SCRN1) as well as low levels of tumor suppressors such as Ret proto-oncogene (RET) and Rho guanine nucleotide exchange factor 12 (ARHGEF12) in CRC patients." (PMID 37228491, 2023). "Although these were not sensitive to anti-RSPO3 treatment only, the combination of anti-RSPO3 with paclitaxel synergistically reduced tumor growth in most cases, being accompanied by reduced nuclear β-catenin, proliferation and CSC frequency against enhanced differentiation." (PMID 34663878, 2021). "However, when anti-RSPO3 antibodies were administered alone, they failed to reduce tumor progression." (PMID 34367990, 2021).
cancer (34 papers, 2016 to 2025). A tumor composed of atypical neoplastic, often pleomorphic cells that invade other tissues. "Enhanced proliferation of gastric stem cells driven by RSPO3 upon H.pylori infection might contribute to this increased risk for cancer development." (PMID 34663878, 2021). "DEG analysis revealed higher expression levels of CRC markers such as CEACAM6, SPINK1, TGFBI and RSPO3 in the cancer cell group." (PMID 40355592, 2025). "The most common mutation affecting downstream components in the aberrant cancer Wnt/β-catenin signaling pathway is seen in the gene-encoding adenomatous polyposis coli (APC), with such mutations being seen in RNF43-, ZNRF3-, and RSPO3-mediated cancers." (PMID 39125653, 2024). "Other groups have investigated anti-Wnt1 or R-spondin 3 (RSPO3) antibodies to target the Wnt/β-catenin pathway in cancer." (PMID 38612911, 2024). "RSPO3 has been identified as a driver of various cancers, such as bladder cancer, breast cancer, and ovarian cancer." (PMID 37932819, 2023). "PDAC cells and spindle-shaped cells lining the cancer cells were stained positive for RSPO3 in Grade1 PDAC tissue." (PMID 35272688, 2022). "The three main conclusions of this study are i) that the transmembrane phosphatase PTPRK, whose gene is found in prominent cancer-related fusion events with the ZNRF3 negative regulator RSPO3, is itself a positive regulator of ZNRF3." (PMID 31934854, 2020). "One of the first reports to link RSPO3 with cancer showed RSPO3 to be frequently upregulated by genomic integration of the mouse mammary tumour virus (MMTV)." (PMID 30987640, 2019). "To correlate RSPO3 levels and cancer outcomes directly, we stratified men according to RSPO3 expression and compared their biochemical recurrence-free survival rates between the two strata." (PMID 30987640, 2019). "Our results appear to be at odds with these reports; however, we feel this contradiction highlights a potentially complex role for RSPO3 in cancer overall." (PMID 30987640, 2019). "RNF43, ZNRF3, RSPO2 or RSPO3 alterations in breast, colorectal, gastric, pancreatic and other cancers activate the Wnt/β-catenin signaling." (PMID 29312609, 2017). "Identification of RSPO2/RSPO3 translocations in cancer provides not only an attractive target for Wnt pathway inhibition using antibody approaches but also an intuitive predictive biomarker for RSPO2/RSPO3 antibodies." (PMID 27338477, 2016). "In addition to and most likely due to the abilities of LGR5 and RSPO3 to regulate β-catenin signaling, they are also employed as cancer stem cell markers." (PMID 37998393, 2023). "RSPO3 has been reported as being widely involved in cancer progression." (PMID 36755806, 2023). "In this study, immunohistochemistry showed that CAFs proximal to the cancer cells expressed RSPO3 along with αSMA, suggesting that a specific population of myCAFs located close to cancer cells maintain their differentiation signatures through secreting niche factors." (PMID 35272688, 2022). "However, myCAFs are located in direct proximity to cancer cells, and recent studies reported that stromal myofibroblasts secrete RSPO3 to support gastrointestinal epithelial stem cells." (PMID 35272688, 2022). "Clinical trials addressing the efficacy of indirect and direct RSPO targeting strategies through PORCNi and anti-RSPO3 antibodies respectively will hopefully provide more insight beneficial to the development of novel treatment strategies against RSPO driven cancer." (PMID 34663878, 2021).
cancer (continued). "Recognizing the promising clinical potential of RSPOs as novel therapeutic targets, a clinical trial has been set-up that tested the safety and efficacy of the neutralizing monoclonal anti-RSPO3 antibody OMP131-R10 (Rosmantuzumab) in cancer patients with advanced solid tumors and metastatic CRC." (PMID 34663878, 2021). "One recent computational study showed that both MPPED2 and RSPO3 play a role in carcinogenetic process across cancer types, which suggests that they might be part of the active processes underlying colorectal carcinogenesis." (PMID 30846004, 2019). "RSPO3 has been reported as a regulatory gene in the cancer tissue as a cyclical gene." (PMID 29301256, 2018). "Indeed, mutations of RNF43/ZNRF3 and recurrent translocations of RSPO2/RSPO3 have recently been identified in various cancers." (PMID 27338477, 2016). "With further studies exploring downstream signaling mechanisms of RSPO3, as well as contribution to other cancers, we may appreciate the full and seemingly complex role of RSPO3 in the future with an ultimate goal of capitalizing on its molecular profile as a biomarker or a therapeutic target." (PMID 30987640, 2019). "Together with its ligand RSPO3, the LGR5 receptor promotes β-catenin signaling in cancer cells predominantly via membrane clearance of two endogenous negative regulators of β-catenin signaling: the transmembrane ubiquitin ligases ZNRF3 and RNF43." (PMID 37998393, 2023). "In human breast, RSPO3 is expressed in ALDH+ cells, a cell population that has been proposed to represent (cancer) stem cells and luminal progenitor cells." (PMID 34663878, 2021). "In neuronal cells, the cancer-related gene SLIT2 was found to be upregulated, as were six other cancer-related genes (PDGFRA, DDR2, RSPO3, IL6ST, NTRK2, and HEY1) in cardiomyocytes and one cancer-related gene (HSD3B1) in hepatocyte-like cells." (PMID 32127560, 2020). "Pan-cancer analysis revealed the expression patterns of FNDC1 and RSPO3 in solid cancers." (PMID 36755806, 2023). "Thus, in addition to the RSPO3 proteins, HMGA1 and TFAP4 activate the WNT/β-catenin pathway, stimulate cell migration and invasion and promote cancer progression." (PMID 34021172, 2021).